LGI1 (leucine rich glioma inactivated 1)
Diseases named in the same sentence as LGI1 in open-access papers (continued):
Sharing a sentence is not in itself a finding about the gene and the disease.
encephalitis (continued). "In addition, these 20 patients with LGI1 encephalitis were classified into three subgroups: 6 patients with anti-LGI1 antibody only in serum, 3 with anti-LGI1 antibody only in CSF, and 11 patients with anti-LGI1 antibody in serum and CSF." (PMID 37644514, 2023). "The ROC curve also indicated that the combination of PDCD1 and ICAM1 could predict unfavorable prognosis of LGI1 encephalitis patients at one-year follow-up more accurately than either PDCD1 or ICAM1 alone (AUC = 0.936 p = 0.003 vs. AUC = 0.821 p = 0.028; AUC = 0.778 p = 0.052)." (PMID 37644514, 2023). "Moreover, he presented with FBDS, which is common in anti-LGI1 encephalitis." (PMID 37383232, 2023). "Thus, these brain regions with abnormal PET signals in the present study may also be related to the anti-LGI1 encephalitis." (PMID 35711267, 2022). "Clinically, therapies targeting B cells have led to better clinical outcomes than general immunosuppression with corticosteroids in MuSK-MG and anti-LGI1 encephalitis, therefore we conclude that IgG4-AID may require different treatment strategies than classical antibody-mediated autoimmunity." (PMID 35401530, 2022). "Therefore, an initial diagnosis of anti-LGI1 encephalitis was made." (PMID 35645969, 2022). "Thus, we focused on patient relapse rate and also identified factors that may predict the subsequent relapse in anti-NMDAR, anti-GABABR and anti-LGI1 encephalitis." (PMID 35757705, 2022). "However, the roles of these brain regions in anti-LGI1 encephalitis need to be further explored." (PMID 35711267, 2022). "Therefore, uncertainty arose as to whether the patient had both anti-LGI1 encephalitis and NS or whether the LGI1 antibody and LE manifestations were due to the NS." (PMID 35645969, 2022). "Thus, the important findings of the present study were that non-CD patients presented similar patterns of metabolic abnormality as those of CD patients, though the PET signals related to anti-LGI1 encephalitis metabolic abnormality were unable to be detected in them." (PMID 35711267, 2022). "Notably, elevated CXCL13 levels in CSF are specific to anti-NMDAR encephalitis instead of anti-LGI1 encephalitis, which may be due to the different IgG subtypes between the two diseases." (PMID 35937071, 2022). "Thus, p38α/M-CSF inflammatory signaling pathway might fine-tune anti-LGI1- and anti-CASPR2-associated encephalitis." (PMID 35083659, 2022). "Also, patients with LGI1 encephalitis showed unaltered numbers of LGI1 antigen-reactive T cells." (PMID 33442772, 2021). "In this observational cohort study, patients with anti-leucine-rich glioma-inactivated 1 (LGI1), anti-N-Methyl-D-aspartic acid receptor (NMDA-R), anti-gamma-aminobutyric acid B receptor (GABA-B-R) or anti-contactin-associated protein-like 2 (CASPR-2) encephalitis were included." (PMID 34546417, 2021). "Therefore, epitopes of anti-LGI1 encephalitis are relatively more complex and diverse." (PMID 34691026, 2021). "However, the small sample size of patients with LGI1-Ab encephalitis who had SD may have a bias on results of statistical analysis." (PMID 32849186, 2020). "Anti-LGI1 Ab encephalitis may recur or become chronic, as well as legacy cognitive sequelae." (PMID 33162923, 2020). "However, the neural mechanisms underlying memory deficits, seizures and neuropsychiatric abnormalities in anti-LGI1 encephalitis remain unclear." (PMID 32317923, 2020). "Thus, the functional connectivity reduction in STG may lead to abnormal memory capacity and cognitive impairments in anti-LGI1 encephalitis patients." (PMID 32317923, 2020). "Anti-LGI1 encephalitis is a type of AE whose gut microbiota remains unclear." (PMID 33193049, 2020). "Indeed, numerous case reports have documented LGI1 encephalitis misdiagnosed as Alzheimer’s disease, Creutzfeld-Jacob Disease and Dementia with Lewy Bodies before further investigation elucidated the true cause and led to reversal of the cognitive impairment with immunotherapy." (PMID 32873782, 2020).
encephalitis (continued). "However, it is unknown whether B cells within the CNS contribute to the ongoing pathogenesis of LGI1 antibody encephalitis." (PMID 32029531, 2020). "Besides, we did not clarify whether there is a cause–effect relationship between the gut microbiota and anti-LGI1 encephalitis." (PMID 33193049, 2020). "In this study, we identified that patients with anti-LGI1 encephalitis exhibit decreased functional connectivity in hippocampus compared with normal controls, confirming that the alteration of the hippocampus may be related to the development of memory disorders." (PMID 32317923, 2020). "However, we only identified two cases of anti-LGI1 encephalitis among 31 cases (6%)." (PMID 31694559, 2019). "Hearing loss has been reported in other types of autoimmune encephalitis as well, such as in Kelch-like protein-11, NMDA, LGI1, GABAA, and GFAP encephalitis." (PMID 41598359, 2026). "The patient was diagnosed with anti-LGI1 and anti-CASPR2 positive encephalitis and initiated on IVMP combined with efgartigimod (10 mg/kg per week for a total of four doses) for treatment." (PMID 41019070, 2025). "The patient group with anti-LGI1/CASPR2 encephalitis included 107 patients with anti-LGI1 encephalitis and 43 patients with anti-CASPR2 encephalitis." (PMID 40131535, 2025). "Among the various AE, anti-NMDAR encephalitis is the most prevalent (approximately 54%–80% of AE cases), followed by anti-leucine-rich glioma inactivated protein 1 (LGI1) encephalitis and anti-gamma-aminobutyric acid type B receptor (GABABR) encephalitis." (PMID 40735277, 2025). "Subsequently, various subtypes of AE were recognized, including leucine-rich glioma inactivated 1 (LGI1) encephalitis, gaminobutyric acid type B receptor (GABABR) encephalitis, and other types of encephalitis." (PMID 40093740, 2025). "18F‐FDG PET/CT, for example, discloses characteristic patterns in Leucine‐rich glioma‐inactivated 1 (LGI1)‐ and N‐methyl‐D‐aspartate receptor (NMDAR)‐mediated encephalitis." (PMID 41153078, 2025). "Here, we present the case of a patient with anti-LGI1 encephalitis, in which the CASE score was beneficial in making clinical judgment of relapse amidst the scarcity of typical biomarkers of anti-LGI1 encephalitis." (PMID 41164023, 2025). "We draw the following conclusions from our work: The efficacy of IVIG and PE additional to ivMP in patients with anti-NMDAR, -LGI1 and -CASPR2 encephalitis appears to be comparable." (PMID 40131535, 2025). "In a comparison of the most common subtypes of AE (anti-NMDAR, anti-LGI1, and others), anti-NMDAR encephalitis was found to be more prevalent in younger patients than in other subtypes (P < 0.001)." (PMID 40977726, 2025). "Previous studies have indicated that patients diagnosed with anti-mGluR1 encephalitis have a poorer prognosis compared with other autoimmune encephalitis, such as anti-mGluR5 encephalitis, anti-NMDAR encephalitis, or anti-LGI1 encephalitis." (PMID 40771880, 2025). "The American Society for Apheresis (ASFA) concluded that PE is probably effective in treating AE, such as LGI1 and CASPR2 encephalitis." (PMID 40301313, 2025). "In conditions like anti‐LGI1 encephalitis and anti‐NMDAR encephalitis, autoantibodies target and disrupt these proteins, leading to epileptic seizures." (PMID 40542581, 2025). "Temporal lobe seizures are characteristic of LGI1- and CASPR2-Ab encephalitis, while status epilepticus is a frequent occurrence in GABAAR- and GABABR-Ab AE." (PMID 40274643, 2025). "We compared NLR between anti-NMDAR and anti-LGI1 encephalitis and found that NLR and leukocyte counts were significantly higher in patients with anti-NMDAR encephalitis (p < 0.05)." (PMID 39539648, 2024). "Taken together, in patients with LGI1 and CASPR2 antibody encephalitis, our results identify CSF as a compartment with a remarkably high frequency of clonally expanded autoantigen-reactive ASCs whose BCR maturity appears dominantly acquired outside the CNS." (PMID 38319973, 2024).
encephalitis (continued). "After treatment with immunotherapies, up to 40% of patients with both LGI1 and CASPR2 antibody encephalitis experience relapses and residual neurocognitive impairments, which affect quality of life and lead to disability." (PMID 38319973, 2024). "Agitation and thought blocking were typical psychiatric phenotypes in all encephalitis with different antibodies (50% in anti-NMDAR encephalitis, 70% in anti-LGI1 encephalitis, and 56% in anti-GABAB encephalitis)." (PMID 37945763, 2024). "It is followed by anti–leucine-rich glioma-inactivated 1 (LGI1) encephalitis and anti–γ-aminobutyric acid-B receptor (GABABR) encephalitis." (PMID 39421741, 2024). "Their diagnoses were LGI1‐antibody encephalitis (n = 3), CASPR2‐antibody encephalitis (n = 1), and seronegative AE (n = 1)." (PMID 38189625, 2024). "More specifically, a higher mortality is described for anti-GABABR encephalitis (41.7%), followed by anti-NMDAR encephalitis (4–10%), and anti-LGI1 encephalitis (2.8%)." (PMID 38194197, 2024). "In this retrospective study, we collected clinical data from 84 PWAE, including cases of anti-NMDAR, anti-LGI1, anti-CASPR2, anti-GABABR, anti-GAD65 antibody encephalitis, and AE with co-existence of multiple anti-neuronal antibodies." (PMID 39539648, 2024). "GlycA levels were higher in NMDAR‐ and CASPR2‐antibody patients but lower in LGI1‐antibody patients, while UFA levels were decreased in LGI1‐antibody encephalitis only." (PMID 39012808, 2024). "A retrospective observational study on 100 patients described a global mortality rate of 15% for anti-NMDAR, anti-LGI1, and anti-GABABR encephalitis together." (PMID 38194197, 2024). "In this study, we compared the clinical features of COVID-19-related encephalitis with those of HSV-1, HHV-3, anti-NMDAR antibody, anti-LGI1 antibody, and anti-GABAB antibody encephalitis, which are currently the most prevalent types of encephalitis worldwide." (PMID 38772979, 2024). "However, some cases of anti-LGI1 and anti-CASPR2 encephalitis may be associated with thymomas." (PMID 39539648, 2024). "Here, we present three cases of AE (one each of anti–LGI1 antibody encephalitis, anti-GABABR encephalitis, and anti–NMDAR antibody encephalitis) that were treated with four cycles of efgartigimod." (PMID 39421741, 2024). "We analyzed the clinical characteristics of PWAE who developed acute symptomatic seizures, including those with anti-NMDAR, anti-LGI1, anti-CASPR2, anti-GABABR, anti-GAD65 encephalitis, and AE with the co-existence of multiple anti-neuronal antibodies." (PMID 39539648, 2024). "The patient cohort (n = 238) comprised 162 DRE patients, and 76 AE patients including 27 with CASPR2‐, 29 with LGI1‐, and 20 with NMDAR‐antibody encephalitis." (PMID 39012808, 2024). "Seizures often present as a prominent symptom in cases of LGI1 and glutamic acid decarboxylase (GAD) antibody encephalitis, while they manifest as a late-stage symptom in cases of N-methyl-D-aspartate receptor (NMDAR) antibody encephalitis." (PMID 38528535, 2024). "Among these, anti-LGI1 and anti-CASPR2 encephalitis are related to IgG4 as the dominant immunoglobulin subtype." (PMID 38698867, 2024). "In this study, ResNet18, VGG16, and ResNet50 models were used to discriminate between LGI1 and GABAB receptor antibody encephalitis." (PMID 37592180, 2023). "A few studies have reported varying degrees of cognitive impairment in anti-NMDAR encephalitis, anti-GABA receptor encephalitis, and anti-LGI1 encephalitis." (PMID 37360339, 2023). "Based on the classification results of the ResNet18 model, it was found that the heatmap generated by Grad-CAM included the MTL and BG, indicating that this model focused on the MTL and BG to discriminate between LGI1 and GABAB receptor antibody encephalitis." (PMID 37592180, 2023). "The hypermetabolism of the MTL was the most remarkable feature in our study diagnosed with anti-GABABR, LGI1, HU, anti-Ma and anti-Ta, and anti-NMDAR encephalitis, which was similar to prior reports." (PMID 37986052, 2023).
encephalitis (continued). "Compared to other autoimmune encephalitides, such as anti-mGluR5 encephalitis, anti-NMDAR encephalitis, or anti-LGI1 encephalitis, poorer outcomes are observed in patients diagnosed with anti-mGluR1 encephalitis." (PMID 37139064, 2023). "This evidence implied that the metabolic pattern was similar for LGI1 and GABAB receptor antibody encephalitis." (PMID 37592180, 2023). "In conclusion, our study described, compared, and analysed the clinical features, treatment, and prognosis of patients with anti-NMDAR, anti-GABABR, anti-LGI1 and anit-CASPR2 encephalitis." (PMID 38152405, 2023). "CSF levels of T-tau are lower in encephalitis with antibodies against voltage-gated potassium channels (VGKC), LGI1 and other NSAs compared to CJD and discriminate well between NSA-AEs and CJD." (PMID 36979644, 2023). "Metabolism in the MTL and BG was important for discriminating between LGI1 and GABAB receptor antibody encephalitis." (PMID 37592180, 2023). "The proportions of relapse for anti-NMDAR, anti-LGI1, anti-GABABR, and anti-CASPR2 encephalitis were 14.6%, 4%, 63.2%, and 14.3%, respectively, at the last follow-up." (PMID 38152405, 2023). "In our cohort, 52.2% of patients had CSF pleocytosis (70.8% for anti-NMDAR encephalitis,18.5% for anti-LGI1 encephalitis, 66.7% for anti-GABABR encephalitis and 16.7% for anti-CASPR2 encephalitis)." (PMID 38152405, 2023). "The onset ages of anti-GABABR, anti-LGI1 and anti-CASPR2 encephalitis were relatively older compared to anti-NMDAR encephalitis, and men accounted for more cases." (PMID 38152405, 2023). "One of the most frequent forms of encephalitis (AIE) is anti-NMDAR encephalitis, which is followed by anti-Leucine-rich glioma inactivated 1 (anti-LGI-1) and anti-Gamma-amino butyric acid receptor (anti-GABAR) encephalitis." (PMID 37360339, 2023). "However, the weight and height of one patient with LGI1 antibody encephalitis were unknown." (PMID 37592180, 2023). "In general, the ResNet18 model is a potential approach for discriminating between LGI1 and GABAB receptor antibody encephalitis." (PMID 37592180, 2023). "ALE has many subtypes, and leucine-rich glioma-inactivated 1 (LGI1) antibody encephalitis and gamma-aminobutyric acid B (GABAB) receptor antibody encephalitis are two typical subtypes." (PMID 37592180, 2023). "Multiple studies have revealed that the MTL and BG are common abnormal metabolism regions for LGI1 and GABAB receptor antibody encephalitis, consistent with the findings of this study." (PMID 37592180, 2023). "Among these 81 patients, 64 patients with LGI1 antibody encephalitis (58.27 ± 12.62 years, 44 males) and 17 patients with GABAB receptor antibody encephalitis (52.18 ± 12.19 years, 12 males) were verified using antibody testing." (PMID 37592180, 2023). "The positivity of anti-LGI1 antibodies in serum and CSF together with metabolic impairment revealed on FDG-PET led to a final diagnosis of anti-LGI1 encephalitis." (PMID 37275973, 2023). "Among them, 48 (46.6%) had anti-NMDAR encephalitis, 28 (27.2%) had anti-LGI1 encephalitis, 20 (19.4%) had anti-GABABR encephalitis, and 7 (6.8%) had anti-CASPR2 encephalitis." (PMID 38152405, 2023). "In our study, the proportions of patients with a good prognosis for anti-NMDAR, anti-LGI1, anti-GABABR, and anti-CASPR2 encephalitis were 87.5%, 92.0%, 42.1%, and 71.4%, respectively." (PMID 38152405, 2023). "Anti-LGI1, anti-CASPR2, and anti-GABABR encephalitis mainly showed a T2-FLAIR hyperintense signal in the medial temporal lobe or the hippocampus." (PMID 38152405, 2023). "Hypermetabolism in the basal ganglia and medial temporal lobe is common in anti-LGI1 and anti-CASPR2 encephalitis." (PMID 38152405, 2023). "A total of 100 hospitalized patients with anti-NMDAR, anti-LGI1, or anti-GABABR encephalitis were included in the final analysis." (PMID 35320933, 2022).
encephalitis (continued). "Patients with anti-NMDAR, anti-LGI1, and anti-GABABR encephalitis were recruited from the Neurology Department of the First Hospital of Jilin University from March 2015 to November 2021." (PMID 35320933, 2022). "We isolated the exosomes from CSF fluid of 13 patients with anti-NMDA receptor encephalitis, 11 patients with anti-GABAB receptor encephalitis, 9 patients with anti-LGI1 encephalitis, 8 patients with anti-CASPR2 encephalitis, and 12 control individuals." (PMID 35083659, 2022). "In total, 100 hospitalized patients with anti-NMDAR, anti-LGI1, and anti-GABABR encephalitis were included in the final analysis after 10 patients were excluded based on the exclusion criteria." (PMID 35320933, 2022). "Univariate analysis of factors associated with acute symptomatic seizures in patients with anti-NMDAR, anti-LGI1, and anti-GABABR encephalitis." (PMID 35281052, 2022). "We aimed to investigate the mortality rate and identify the predictors of death in patients with anti-NMDAR, anti-LGI1, and anti-GABABR encephalitis." (PMID 35320933, 2022). "This retrospective, observational study evaluated the clinical features of acute symptomatic seizures and the predictors of the development of chronic epilepsy in patients with anti-LGI1, anti-NMDAR, and anti-GABABR encephalitis." (PMID 35281052, 2022). "Fourth, only patients with anti-NMDAR, anti-LGI1 and anti-GABABR encephalitis were included in our study." (PMID 35281052, 2022). "In the present study, 15% of patients with anti-NMDAR, anti-LGI1, or anti-GABABR encephalitis died during a median follow-up of 18 months." (PMID 35320933, 2022). "No other variable was found to be associated with mortality in this cohort of patients with anti-NMDAR, anti-LGI1, and anti-GABABR encephalitis." (PMID 35320933, 2022). "In summary, our data showed an overall mortality rate of 15% in patients with anti-NMDAR, anti-LGI1, or anti-GABABR encephalitis." (PMID 35320933, 2022). "Univariate analysis of factors associated with the development of epilepsy in patients with anti-NMDAR, anti-LGI1, and anti-GABABR encephalitis." (PMID 35281052, 2022). "In this cohort, 37 patients were positive for anti-NMDAR (43%), 34 patients (40%) for anti-LGI1, and 15 patients for anti-GABABR (17%) encephalitis." (PMID 35281052, 2022). "A significant difference was observed in terms of seizure type among groups with anti-NMDAR, anti-LGI1 and anti-GABABR encephalitis, which was in line with the results of prior literature." (PMID 35281052, 2022). "In the same year that CASPR2 antibodies were identified as also being part of the VGKC complex in patients with LGI1 encephalitis, patients with CASPR2-positive encephalitis were clinically characterized by confusion, amnesia, and hallucinations." (PMID 33026492, 2021). "Anti-NMDAR patients presented with more severe disability at admission compared to anti-LGI1, anti-GABABR and anti-Caspr2 encephalitis." (PMID 33767656, 2021). "Due to the low incidence of AE, especially rare LGI1, GABAR, and anti-a-amino-3-hydroxy-5-methyl-4-isoxazolepropionic acid receptor (AMPAR) encephalitis classes, clinical studies with large sample sizes are rare, both in China and abroad." (PMID 34135845, 2021). "We identified anti-NMDAR encephalitis, anti-LGI-1 encephalitis, anti-GABAbR encephalitis, and anti-CASPR encephalitis as the most common subtypes in our cohort, which is similar to previous studies in China and in Western countries." (PMID 33679765, 2021). "During the follow-up period, 33 (17.84%) patients experienced a relapse, 19 with anti-NMDAR encephalitis, 7 with anti-LGI1 encephalitis, 3 with anti-CASPR2 encephalitis, 3 with anti-GABABR encephalitis, and 1 with anti-AMPAR encephalitis." (PMID 34135845, 2021). "Chorea or hemichorea was also described in the context of leucine-rich-glioma-inactivated-1 (LGI1)- and CASPR2-encephalitis, sometimes as the main clinical or presenting symptom." (PMID 33324912, 2020).